PMS2 (PMS1 homolog 2, mismatch repair system component)
Diseases named in the same sentence as PMS2 in open-access papers (continued):
Sharing a sentence is not in itself a finding about the gene and the disease.
bone sarcoma (1 paper, 2022). A sarcoma that arises from the bone. "PMS2 alterations were also seen in two patients with GIST, one patient in the bone sarcoma cohort (giant cell tumor of bone), and one patient in the uterine sarcoma cohort (leiomyosarcoma)." (PMID 36741731, 2022).
Burkitt lymphoma (1 paper, 2018). A rare form of malignant mature B-cell non-Hodgkin lymphoma. "Six of PMS2-deficient patients had a recent history of high-grade malignant glioma, and one had a recent history of Burkitt’s lymphoma." (PMID 30013564, 2018).
celiac disease (1 paper, 2021). An autoimmune genetic disorder with an unknown pattern of inheritance that primarily affects the digestive tract. "One patient with a tumor with loss of expression of MLH1 and PMS2 had celiac disease; none of the others had SBA-related diseases." (PMID 34944998, 2021).
Cervical tumor (1 paper, 2025).
Chronic Myeloid Leukaemia (1 paper, 2021). "The BCR-ABL positive CML (Chronic Myeloid Leukaemia) cells also lower the expression of mlh1 and pms2 and induce point mutations thus affecting the mismatch repair mechanisms." (PMID 33980898, 2021).
cutaneous squamous cell carcinoma (1 paper, 2021).
dysplasia (1 paper, 2018). A usually neoplastic transformation of the cell, associated with altered architectural tissue patterns. "A total of 81.8% and 81.8% patients with EAC, 32.4% and 35.1% patients with dysplasia, and 50% and 54.5% patients without dysplasia had loss of MLH1 and PMS2 expression, respectively." (PMID 29972732, 2018). "Significant but negative correlation was found only for MLH1/PMS2 expression and only in dysplasia group." (PMID 29972732, 2018). "Our hypothesis that loss of protein expression would be higher in advanced stages of BE was refuted, since we found loss of MLH1/PMS2 expression in all three groups, most commonly in EAC group but also in 50% of patients without dysplasia." (PMID 29972732, 2018).
endometrial adenocarcinoma (1 paper, 2018).
gall bladder cancer (1 paper, 2019). "In a separate study of gall bladder cancer, we found the same essential splice site PMS2 mutation (chromosome 7:6043690C>G) in a Korean patient whose gall bladder cancer exhibits microsatellite instability (E.W.S. and S. Seshagiri, manuscript in preparation)." (PMID 31802016, 2019).
gastric tumor (1 paper, 2022). "This variant was identified in a patient (ID 573) with a gastric tumor diagnosed at age 44 and CRC diagnosed at age 49 with loss of MLH1/PMS2 expression and methylated MLH1." (PMID 36077770, 2022).
glioneuronal tumor (1 paper, 2019). "In this case, a 13-yr-old developed an ultra-hypermutated malignant glioneuronal tumor and tumor sequencing identified two PMS2 variants." (PMID 31604779, 2019).
glomerulosclerosis (1 paper, 2022). A hardening of the kidney glomerulus caused by scarring of the blood vessels. "However Only one individual (U007) had no family history of cancers nor a familial pathogenic variant but was found to be a carrier of a pathogenic variant in PMS2 gene as a secondary finding of her whole-exome sequencing as part of the workup for hereditary glomerulosclerosis she has." (PMID 36421850, 2022).
granulosa cell tumor (1 paper, 2017). A slow-growing, malignant tumor, characterize by the presence of granulosa-like cells and Call-Exner bodies, that is almost always found in the ovary. "The results of this case study indicated that although FOXL2 402C > G mutation determines the development of granulosa cell tumor, PMS2 N775L mutation may be the initial driver of carcinogenesis." (PMID 28347324, 2017). "The results of this case study indicated that although FOXL2 402C > G mutation determines the development of granulosa cell tumor, PMS2 mutation may be the initial driver of carcinogenesis." (PMID 28347324, 2017).
ICF syndrome (1 paper, 2023).
infertile (1 paper, 2012). "Further analysis based on 450 infertile men revealed significant associations of MLH1 rs4647269 and PMS2 rs1059060 with sperm DNA fragmentation." (PMID 22594646, 2012).
Insulin resistance (1 paper, 2017). Increased resistance towards insulin, that is, diminished effectiveness of insulin in reducing blood glucose levels. "Five SNVs in genes AABR06087018.1, Pms2, Zfp866, Gatad2a and Daglb were found to be exclusively associated with insulin resistance." (PMID 28130354, 2017).
intestinal tumors (1 paper, 2017). "A chromosome 7 CNA deletion hotspot shared by Mlh3, Pms2 and Mlh1 mutant MEFs was also seen that had been previously identified in Mlh3−/−;Pms2−/− deficient intestinal tumors." (PMID 29069730, 2017). "Next, to assess SSA, we used gamma-irradiation to promote endogenous DSBs and show that Mlh1, Pms2 and Mlh3 mutations suppress CNAs, including recurrent CNA hotspots that we previously identified in mouse dMMR intestinal tumors." (PMID 29069730, 2017). "Furthermore, an Mlh1 (but not other MutL homologue) mutation dependent chromosome 12 CNA amplification hotspot, which had also been previously identified in Mlh3−/−;Pms2−/− intestinal tumors, was observed." (PMID 29069730, 2017).
intrahepatic cholangiocarcinoma (1 paper, 2019). A carcinoma that arises from the intrahepatic bile duct epithelium in any site of the intrahepatic biliary tree.
Legius syndrome (1 paper, 2022). Legius syndrome, also known as NF1-like syndrome, is a rare, genetic skin pigmentation disorder characterized by multiple cafC)-au-lait macules with or without axillary or inguinal freckling.
lobular carcinoma (1 paper, 2013). "One patient with lobular carcinoma had two CDH1 mutations and one ERBB2 mutation at ~16% allelic fraction, as well as a distinct set of mutations in PTEN, BRCA2 and PMS2 at ~5% allelic fraction." (PMID 24326041, 2013).
lupus nephritis (1 paper, 2013). Glomerulonephritis in the context of systemic lupus erythematosus. "An additional six genes showed an association with lupus nephritis with p <0.001 (PMS2, TNIP1, CARD11, ITGAM, BLK and IRAK1)." (PMID 24386384, 2013).
male infertility (1 paper, 2012). The inability of the male to effect fertilization of an ovum after a specified period of unprotected intercourse. "Meanwhile, we also identified a possible contribution of PMS2 rs1059060 to the risk of male infertility with normal sperm count." (PMID 22594646, 2012). "Based on a case-control study consisting of 480 controls and 768 patients with normal sperm count, we found that PMS2 rs1059060 was significantly associated with male infertility with normal sperm count." (PMID 22594646, 2012).
Medullary carcinoma (1 paper, 2025). "Immunohistochemical patterns differ between medullary carcinoma and other poorly differentiated adenocarcinomas.8) Medullary carcinoma often shows loss of MLH1 and PMS2, whereas poorly differentiated adenocarcinomas typically do not." (PMID 41030825, 2025).
mixed cell type cancer (1 paper, 2022). A cell type cancer that has_material_basis_in abnormally proliferating cells derived_from two germinal layers of tissue. "The non-endometrioid histology cancer types found in patients with MSH6 mutations included serous (n = 1), neuroendocrine (n = 1), dedifferentiated (n = 1), and mixed type (n = 1) cancers, whereas only one case of mixed cell type cancer was found among patients with PMS2 mutations." (PMID 35884469, 2022).
multinodular goiter (1 paper, 2024). Nodular goiter characterized by more than one discrete tissue mass.
myelodysplastic syndrome (1 paper, 2025). A clonal hematopoietic disorder characterized by dysplasia and ineffective hematopoiesis in one or more of the hematopoietic cell lines. "Overall, 16 patients (17.2%) had pathogenic variants, including FANCA, BRCA2, PMS2, ELANE, G6PC3 and VPS13B in patients with idiopathic neutropenia, and GATA2 in patients with suspected myelodysplastic syndrome." (PMID 40358701, 2025).
non-small cell lung carcinoma (1 paper, 2024). A group of at least three distinct histological types of lung cancer, including non-small cell squamous cell carcinoma, adenocarcinoma, and large cell carcinoma. "This comprehensive approach aims to shed light on the involvement of the PMS2 gene in the complex landscape of brain metastasis in non-small cell lung cancer." (PMID 38714954, 2024). "The association of the PMS2 gene with brain metastasis in non-small cell lung cancer has not been investigated to date." (PMID 38714954, 2024).
oral cancers (1 paper, 2021). "An overexpression of PMS2 was observed in N0/1 tumors and in oral cancers found in unusual locations." (PMID 33247565, 2021).
ovarian clear cell cancer (1 paper, 2022). An invasive malignant neoplasm that arises from the ovary and is characterized by a predominance of clear and hobnail malignant epithelial cells. "Ovarian clear cell carcinoma (OCCC) (n = 28) and endometrial clear cell carcinoma (ECCC) (n = 28) samples were evaluated for PD-L1 (in tumoral and peri-tumoral inflammatory cells), MSH6 and PMS2 expression by immunohistochemistry (IHC) study." (PMID 36581850, 2022).
perihilar cholangiocarcinoma (1 paper, 2019).
pilomatricomas (1 paper, 2020). "As multiple pilomatricomas with CTNNB1 mutations have been described in patients with PMS2 germline mutations, we analyzed the stability of microsatellite DNAs BAT25, BAT26, D2S123, D5S354 and D17S250 in two pilomatricomas of the patient (G34dup, T41I) and in the pilomatrical carcinoma." (PMID 32155193, 2020). "Interestingly, analysis of CMMR-D-associated pilomatricomas did not reveal microsatellite instability with markers BAT-26, BAT-25, BAT-40, D2S123, D5S346, D17S250, TGFbRII, D17S787, D18S58 and D18S69 despite mutations of PMS2." (PMID 32155193, 2020).
prostatic adenocarcinoma (1 paper, 2022).
protein (1 paper, 2019).
rectal adenocarcinoma (1 paper, 2023). "Only 6.9% (n = 168) of patients in the total cohort had dMMR rectal adenocarcinoma, and the most common cause of dMMR was a PMS2 deletion (103, 61.3%)." (PMID 37864137, 2023).
seminoma (1 paper, 2024). A radiosensitive malignant germ cell tumor found in the testis (especially undescended), and extragonadal sites (anterior mediastinum and pineal gland). "They reported MMR deficiency, as evidenced by loss of MLH1 and PMS2 expression, in only one seminoma." (PMID 38285100, 2024).
small bowel adenocarcinoma (1 paper, 2018). "Cancer tissue specimens resected from small bowel adenocarcinoma in a Japanese patient showed decreased expression of MLH1 and PMS2 by immunohistochemistry testing." (PMID 30083359, 2018).
small cell carcinoma (1 paper, 2022). A neuroendocrine carcinoma composed of small malignant cells which are often said to resemble "oat cells" under the microscope.
sweat gland tumors (1 paper, 2025). "We have described sweat gland tumors with HRD-associated germline PALB2, BRCA1, and PMS2 mutations." (PMID 40948682, 2025).
testis cancer (1 paper, 2024). "Almost all of the top-performing genes were that of over-expression, with PMS2 in THYM; CARD11, LASP1, STIL, POLE, KMT2C, and CLIP1 in testis cancer; ERC1, WRN, OLIG2, FANCC, and ACSL6 in ACC; and SOX2 and NDRG1 in ESCA leading in performance with AUCs ranging 0.832-0.911." (PMID 38491101, 2024).
thymic lymphomas (1 paper, 2015). "In PMS2-deficient transgenic mice, a much higher rate of mutation was observed after exposure to ionizing radiation as well as thymic lymphomas after treatment with MNU when compared to wildtype animals." (PMID 26036629, 2015).
tubulovillous adenoma (1 paper, 2012). An epithelial neoplasm morphologically characterized by the presence of a villous and a tubular architectural pattern. "In a previous preliminary study we found that tissue samples from patients with large tubulovillous adenomas or adenocarcinomas had reduced Pms2 expression in cell nuclei at the bases of crypts (including the stem cell regions) near these tumors." (PMID 22494821, 2012).
tumor predisposition syndromes (1 paper, 2023). "Nevertheless, in the ClinVar database, two different patients harboring the PMS2 (c.184G>A; p.Gly62Ser) VUS have been reported in association to LS and other hereditary tumor predisposition syndromes." (PMID 37894428, 2023).
uterine tumors (1 paper, 2018).
vascular tumor (1 paper, 2025).
villous adenoma (1 paper, 2025). An epithelial neoplasm morphologically characterized by the presence of a villous architectural pattern.
xeroderma pigmentosum (1 paper, 2019). Xeroderma pigmentosum (XP) is a rare genodermatosis characterized by extreme sensitivity to ultraviolet (UV)-induced changes in the skin and eyes, and multiple skin cancers.